MMP9 (matrix metallopeptidase 9)
Diseases named in the same sentence as MMP9 in open-access papers (continued):
Sharing a sentence is not in itself a finding about the gene and the disease.
cancer (continued). "Furthermore, the fact that isolated deflamin is efficient in inhibiting MMP-9 and reducing cancer cell migration suggests its high potential for a vast array of clinical uses." (PMID 34359533, 2021). "It was understood that MMP-9 expressed by a metastatic cancer cell such as 4T1 could be the indicator of the cancer cell progression; therefore, the inhibition activity of MMP9 by compound (sample) should have corresponded to its cancer cell antiproliferation." (PMID 33800366, 2021). "Obviously, preserving the last property represents a double-edged sword because improved MMP-9 activity could facilitate cancer metastasis too." (PMID 34830212, 2021). "MMP-9 is a member of MMPs that break down the basement membranes through the degradation of type IV collagen, exposing cryptic sites within the matrix and allowing cancer cell invasion." (PMID 34771620, 2021). "Cancer cells corresponding to their histologic grade produced the Matrix Metalloprotein-9 (MMP-9)." (PMID 33850625, 2021). "MMP2 and MMP9 overexpression, and links to the progression of a wide range of cancers, have been well-documented and due to their involvement in the pathophysiology of disease, MMP2 and MMP9 are generally considered as the most important enzymes among the MMPs47,81,84." (PMID 33958632, 2021). "Given the fact that MMP‐9 inhibitors alone lack clinical benefits for cancer therapy, these drugs may become an important therapeutic component in combination settings as shown in our study." (PMID 34486239, 2021). "MMP-2 and MMP-9 play major roles in cancer cell invasion and metastasis." (PMID 34770993, 2021). "However, higher ETS1 and GSK3β were expressed in IOSE-80PC cells, suggesting that phosphorylation of ETS1 is mediated via GSK3β thereby activates MMP9 expression in cancer cells." (PMID 34023818, 2021). "Moreover, CCA-1.1 was found to inhibit cancer cell migration mediated through the inhibition of proteolytic activity from MMP-9 in 4T1 and MCF-7/HER2 cancer cells." (PMID 34181339, 2021). "In addition, matrix metalloproteinase (MMP), ADAMTS1 and Snail are factors associated with cancer migration and invasion; thus, we analyzed MMP-2, MMP-9, ADAMTS1, and Snail expressions in EGFL6 siRNA treated HCT116 and HT29." (PMID 33726836, 2021). "MMP-9 secreted by Ym1+Ly6Chi monocytes may degrade extracellular matrix and promote infiltration of cancer cells into metastatic tissues." (PMID 34163472, 2021). "As long as this isoform of MMP-9 is present, vigilance is needed, as its presence may represent a valid signal of irreversibility for several cancer types." (PMID 35723387, 2021). "MMP-9 and M2 polarization induce cancer cell intravasation and metastasis in vivo." (PMID 33783686, 2021). "The three clusters generated contained genes or proteins involved in apoptosis (BIRC3, BIRC5, PARP1, CASP8, and CASP9), transcriptional dysregulation in cancer (CDKN1B, RELA, CDKN1A, MYC, JUN, and MMP9), and cancer progression (CCND1, CASP3, CTNNB1, WNT1, and VEGFA) pathways." (PMID 34836311, 2021). "Notably, the production of matrix metalloproteinases MMP-2 and MMP-9, which are crucial for cancer cell invasion and metastasis, was significantly suppressed in response to rSmeg-hMIF-hIL-7 treatment." (PMID 34389619, 2021). "MMP-9 is a protease upregulated in various malignant tumors, including NSCLC." (PMID 34689761, 2021). "Consequently, on the basis that MMP9 was the most related gene in OS, as well as its significance in other cancer types, screening of inhibitors targeting MMP9 was urgent and conducted in the following research." (PMID 34261456, 2021).
cancer (continued). "Consequently, the degraded GRK2 activated ERK/MMP-9 signaling pathway, which increased MMP-9 protein levels, to promote cell membrane degradation, facilitating cancer cell migration and invasion." (PMID 33936199, 2021). "Thus, the inhibition of MMP-2 and MMP-9 activities can be employed as an important anti-metastasis strategy to prevent cancer cell dissemination." (PMID 34769032, 2021). "Another neutrophil protease involved in cancer is cathepsin G. It has been shown to be a mediator of MMP-9 activation and promotes TGFβ (Transforming growth factor β) signaling that is important for formation of bone lesions, cancer-induced osteolysis and metastasis." (PMID 33802262, 2021). "High levels of LpCat1 in HCC could inhibit STAT1 expression, up-regulate CyclinD1, CyclinE, CDK4 and MMP-9, and decrease p27kip1 to promote cancer progression." (PMID 34178664, 2021). "Various studies demonstrated that oridonin could inhibit the expression of MMP-2 and MMP-9 in various cancers such as breast, acute myeloid leukemia bone, and ovarian cancer." (PMID 33546106, 2021). "MMP9 participates in ECM remodeling, alteration of cell-cell and cell-ECM interactions, and cleavage of membrane surface proteins and is associated with poor prognosis in cancer patients." (PMID 34101732, 2021). "Moreover, MMP9 has been reported to serve as an important inflammatory mediator in angiocardiopathy, infectious diseases and cancer." (PMID 33892730, 2021). "In addition, the HOXB9-induced upregulated expression of SSP1 and MMP9, two well-known cancer metastasis promoters, was suppressed by TGFβ inhibitor." (PMID 34247196, 2021). "Thus, we offered that the MMP-9 in cancer cells should be constructed as a novel target for an anticancer drug to treat malignant phenotype tumors, which are mainly characterized by HER2-positive and TNBC subtypes." (PMID 34181339, 2021). "Negatively regulated NF-κβ, PI3K/AKT, MAPK/JNK, and STAT pathways and inhibited MMP-7, MMP-9, and VEGF proteins are found to be key markers of the emodin.Like other cancer cell lines, emodin caused mitochondrial dysfunction and decreased mitochondrial membrane potential in colon cancer cell lines." (PMID 34073059, 2021). "These cancer cell models are commonly studied due to the high expression of MMP9 during metastasis." (PMID 33800366, 2021). "In addition, multiple studies in various cancer cell lines showed that UA down-regulates two gelatinases responsible for the breakdown of extracellular matrix involved in cancer metastasis, matrix metalloproteinase 9 (MMP-9), and MMP-2." (PMID 34439409, 2021). "Therefore, we compared gene expression for cancer-associated fibroblast (CAF) markers including MMP2, MMP9, MMP21, TGFA, CXCL12, ITGA3, FAPα, and IL32 in fibroblasts derived from normal skin and MF tumors." (PMID 33941102, 2021). "MMP-9 is a crucial enzyme in cancer metastasis that destroys the extracellular matrix." (PMID 34512336, 2021). "Among these inducers, PMA and TGF-β can increase MMP-9 expression and secretion during cancer cell invasion by activating nuclear factor kappa B (NF-κB) and activator protein 1 (AP-1), as their promoter region contains binding sites for these transcription factors." (PMID 34769032, 2021). "MMP9 plays a main role in cancer cell migration, regulated by miR-335." (PMID 33919449, 2021). "Additionally, MMP-9 comprises the gelatinase sub-family of MMPs and is primarily produced by inflammatory cells and from the stromal cells surrounding a tumor or by the cancer cells themselves." (PMID 34287243, 2021). "Furthermore, the mRNA levels of MMP-2 and MMP-9, extracellular matrix-degrading enzymes required for the cancer invasive process, were significantly downregulated by ETD in a dose-dependent manner." (PMID 33758209, 2021). "MMP-9 plays an important role in the invasion and metastasis of cancer cells." (PMID 34163472, 2021).
cancer (continued). "Numerous studies have demonstrated that the expression of MMP2 and MMP9 in cancer cells could be directly mediated by activation of the PI3K/AKT/mTOR pathway." (PMID 34758823, 2021). "MMP-2 and MMP-9 are two key enzymes in the process of cancer cell invasion and metastasis." (PMID 34659556, 2021). "Given that RPL23 is an RNA-binding protein which can regulate human cancer progress by influencing RNA stability, We then performed experiments to elucidate whether the decreased MMP9 mRNA levels were due to a change in RNA synthesis or decay." (PMID 34926291, 2021). "MMP-2 and MMP-9 can degrade components of the ECM such as type IV collagen to release tension and allow growth and invasion of tumors and as such are implicated in the late stages of cancer." (PMID 33596971, 2021). "Animal studies showed that MMP-9 overexpression contributes to cancer development and progression." (PMID 34439874, 2021). "Finally, metastatic cancer cells in distant tissues typically remain dormant for an extended period, during which infiltrating neutrophils release MMP-9 to promote angiogenesis, triggering the growth of dormant metastases." (PMID 34674757, 2021). "MMP9 is a major mediator of the degradation of extracellular matrix (ECM) proteins such as collagen, fibronectin and laminin, and its activation is a key event in the ECM remodeling process closely associated with cancer cell migration." (PMID 33572115, 2021). "Hence, we constructed an integrated hybrid nanovesicle, cancer cell membrane lipsome (CLip), by fusing Cm and MMP-9-switchable peptide-based charge-reversal liposome membrane (Lipm), thereby utilizing both biomaterials." (PMID 34689761, 2021). "Upregulation of MMP-2 and MMP-9 are particularly noted in cancer cells." (PMID 35366261, 2021). "In addition, knockdown of P4HA1 inhibited the expression of MMP2 and MMP9, which were widely considered to relate to cancer invasion." (PMID 34659558, 2021). "High expression of MMP-9 has been found in many kinds of cancers." (PMID 34122670, 2021). "Furthermore, VPA-treated A549 cells showed decreased expression of CD44v6, MMP-2, and MMP-9 considered as metastasis indicators in cancer." (PMID 34400947, 2021). "5-MTP also inhibits MMP-9 expression and thereby reduces cancer cell invasion." (PMID 33925793, 2021). "The addition of 786O cancer cells led to an increase in MMP9, Gro-α, IL-8, IL-6, HB-EGF, and VEGF-A; and the addition of ccRCC PBMCs led to an increase in PDGF-BB and IL-1β as well as a further increase in MMP-9, Gro-α, IL-8, IL-6, and CCL-2 despite cabozantinib treatment." (PMID 34931665, 2021). "In an attempt to develop peptide-based gelatinase inhibitors to attenuate cancer progression, an in vitro phage display screen with purified MMP9 using a random peptide (CX5-8C) library was used to identify two cyclic decapeptides (CTTHWGFTLC (CTT) and CRRHWGFEFC) targeting MMP2 and MMP9." (PMID 33918106, 2021). "Moreover, the downstream target genes of Akt, including CDK4, MMP‐2 and MMP‐9, are involved in cancer cell proliferation, migration and invasion." (PMID 34709758, 2021). "Interestingly, preventing ERK activation in cancer cells has led to decreased gene expression and enzymatic activity of MMP-9." (PMID 34048471, 2021). "Moreover, lycopene-mediated regulation of expression of MMP-2 and MMP-9 in several cancer cell lines inhibits the cancer growth and proliferation." (PMID 34094892, 2021). "MMP9 has been reported to play an important part in the EMT process of cancer cells." (PMID 33854593, 2021). "Since MMP2 and MMP9 are two of the most characterized MMPs in cancer metastasis, and since Ankrd2 modulates cell motility, we tested the possibility that Ankrd2 might promote invasion by modulating the activity of these MMPs." (PMID 33419058, 2021). "Previous and current studies demonstrate an effect of FQs on the expression level of MMP-9, suggesting that FQs could be a potential therapeutic agent for ameliorating cancer development and dissemination." (PMID 34769032, 2021).
cancer (continued). "Interestingly, NRF2 regulates the expression of MMP9, a protein regulating cell invasion in different cancers, including human HCC." (PMID 34069882, 2021). "MMP-9 plays an important role in cancer cell invasion and tumor metastases." (PMID 34552922, 2021). "Among the various members of the MMP family, MMP2 and MMP9 have major roles in cancer metastasis." (PMID 34211571, 2021). "The value of MMP-9 is evaluated as a biomarker for various specific cancers." (PMID 34771620, 2021). "RECK, a gene involved in suppressing cancer cell migration, invasion, and metastasis, negatively regulates matrix metalloproteinase 9 (MMP9) by directly inhibiting its enzymatic activity and abolishing MMP9 secretion." (PMID 32051475, 2020). "Next, we examined whether Benz could suppress cancer cell motility and invasiveness driven by the expression of MMP9." (PMID 32102440, 2020). "In order to intravasate, cancer cells mainly rely on the MMP-9 they produce." (PMID 32630531, 2020). "Moreover, MMP-9 released by cancer cells which have undergone a full EMT facilitates the intravasation of cancer cells which have been subjected only to a partial EMT." (PMID 32630531, 2020). "In addition to EMT, NOB can inhibit MMP-2 and MMP-9 expressions to suppress the metastasis of cancer cells." (PMID 32380783, 2020). "MMP2 and MMP-9 are matrix metalloproteinases that promote the invasion of cancer cells." (PMID 32550915, 2020). "Therefore, there is an intricate signaling network with feed-forward and feedback loops comprising of NF-κB, PAX7, MyoD, myostatin, miR-486, and MMP-9 that regulate skeletal muscle homeostasis, which is disrupted in cancer." (PMID 31941005, 2020). "However, selective MMP-9 inhibitors, such as hydroxamates, pyrimidine-2,4,6-triones, carboxylic-acid-based inhibitors, and others, have been tested as potential cancer therapies." (PMID 32575507, 2020). "Using RNA extracted from long bones of Gal8-KO mice we found significantly lower (50%) mRNA levels of MMP9 in gal-8 KO mice when compared to WT mice, suggesting that this might also contribute to the resistance of Gal-8 KO mice to develop cancer metastasis." (PMID 32355198, 2020). "Next, as representative examples relevant to a large number of cancers associated with EMT, we examined VIM and MMP9 expression in more detail (assessed by individual RT-qPCR and immune-detection), which have also been examined in the context of EMT-related melanomagenesis." (PMID 32466621, 2020). "The up-regulation of MMP-9 by microvesicles is significant due to its role in extracellular matrix dissolution, which facilitates the breakdown of barriers that normally prevent cancer cells from invading distal sites." (PMID 32948029, 2020). "MMP-9 is also assumed to be important in cancer cell metastasis." (PMID 31621555, 2020). "Interestingly, in the cancer survivor group, MMP9, and Osteopontin, both known to promote disease progression, had significant positive correlations with the marginalization scale of barriers in access to care." (PMID 32587352, 2020). "Cancer cells secrete metalloproteinases (MMPs), such as MMP-9, to degrade the extracellular matrix." (PMID 32155880, 2020). "The role of MMP-9 as a potential biomarker has been studied in various cancers." (PMID 31983189, 2020). "Thus, the combination of Hst and Dox decreased expression of a protein that plays a role in cancer metastasis, which is MMP9 and Rac1." (PMID 32458631, 2020). "MMP-9 is a proteinase involved in cancer cell migration and extravasation." (PMID 31900168, 2020). "This sharpens our hypothesis to the conclusion that both Ixora and Ageratum have cancer cell antiproliferative activity, which is due to the MMP9 inhibition, leading to more selective cancer chemotherapy." (PMID 33066411, 2020). "Additionally, MMP-9, a type IV collagenase, and its high expression is closely correlated with malignant tumor invasion, metastasis and vascular formation, and IP6 and Ins were shown to inhibit the MMP-9 in this model." (PMID 33333775, 2020).
cancer (continued). "We examined whether these compounds could suppress tumoroid growth, MMP9 promoter activities, and cancer cell viabilities by using the tumoroid-based multiplex phenotypic screening system." (PMID 32102440, 2020). "MMP-9 is a zinc-dependent protease that is responsible for degradation of components of the extracellular matrix, such as gelatin, and plays a critical role in cancer metastasis and progression." (PMID 33233689, 2020). "Activation of MMP-2 and MMP-9 is related to PC progression through invasion of cancer cells." (PMID 32349276, 2020). "As NFκB is the key transcription factor for MMP9 expression, we hypothesize that NFκB could participate in regulating cancer cell metastasis by mediating MMP‐9 expression." (PMID 32720731, 2020). "Matrix metalloproteinase-9 (MMP-9) isinvolved in the metastasisof cancer cells." (PMID 33095554, 2020). "Basically, while CD44 recruits MMP-9 at the protrusions of migrating cells, thereby spatially directing MMP-9 proteolytic activity, CD151 facilitates MMP-9-mediated cancer cell motility by mediating integrin endocytosis at the rear or basal-lateral front of migrating cells." (PMID 32630531, 2020). "Therefore, we evaluated the changes in MMP2 and MMP9 expression and activity in the cancer cells by western blotting and gelatin zymography assays, respectively, under the same conditions used in the migration/invasion assays." (PMID 33371405, 2020). "This miRNA may inhibit the MMP-9 expression and then prevents the metastatic activity of the cancer cells." (PMID 33250681, 2020). "Since A. vera has been shown to concomitantly exhibit anti-inflammatory and anti-cancer activities, it appears reasonable to infer that targeting MMP-9 (a known key player in both conditions) could be one of Aloe’s biocomponents mode of action." (PMID 33308217, 2020). "Additionally, MLK1 enhanced cancer cell migration and invasion by epigenetic activation of MMP9 transcription in lung cancer." (PMID 32251318, 2020). "In cancer, MMP9 facilitates the invasiveness and metastatic phenotypes of tumor-supporting cells." (PMID 33096662, 2020). "In addition, the overexpression of MMP9 increases the invasiveness of certain cancer cell lines and is involved in disease progression." (PMID 33096662, 2020). "Six of these validated genes (BIRC5, MK167, MMP9, PLOD2, and TOP2A) have previously been implicated ccRCC,21, 22, 23, 24, 25, 26, 27, 28, 29, 30, 31, 32, 33, 34 while the others have been implicated in other cancers." (PMID 32986937, 2020). "Therefore, MMP9 has become a therapeutic target for various cancers, such as ovarian cancer, cervical cancer, and pancreatic cancer." (PMID 32905356, 2020). "Therefore, reducing the expression of MMP-2 and MMP-9 or its upstream regulatory signaling pathways is essential for the treatment of malignant tumors." (PMID 32922544, 2020). "In addition, BB aqueous extracts reduced the secretion of MMP-9, leading to inhibition of cancer cell invasion." (PMID 32238777, 2020). "Besides, it seems likely that cell-impermeable inhibitors of HSP90 activity are able to downregulate cancer stemness-associated extracellular proteinases, such as MMP2 and MMP9, whose expression, secretion, and activity are dependent on extracellular HSP90." (PMID 32268506, 2020). "EGFR and MMP9 have long been areas of research focus in cancer theranostics." (PMID 33007872, 2020). "CXCL8-induced MMP-9 promotes extracellular matrix degradation, which not only provides the necessary conditions for angiogenesis, but also plays an important role in cancer cell invasion and metastasis." (PMID 32201645, 2020). "Thus, it was indicated that Benz inhibited the transcription and production of MMP9 from the metastatic cancer cells." (PMID 32102440, 2020). "Recently, MMP9 has been identified as a potential biomarker for several cancers 74-78." (PMID 32922167, 2020).